DLK1 (delta like non-canonical Notch ligand 1)
Diseases named in the same sentence as DLK1 in open-access papers (continued):
Sharing a sentence is not in itself a finding about the gene and the disease.
tumor (continued). "The Late Group was administrated at 16 weeks after DEN injection, as expected, seven mice injected with adenovirus for Dlk1 knockdown showed the significant reduction of tumor number, size and weight, as compared to mice injected with control vector." (PMID 27683116, 2016). "Here we demonstrated that knockdown of DLK1 using a tet-inducible short hairpin RNA (shRNA) system significantly inhibited proliferation, spheroid formation and in vivo xenograft tumor growth of human HCC cells." (PMID 27683116, 2016). "A significant decrease in subcutaneous tumor growth in nude mice was observed after restoration of DLK1 in comparison to control cell lines suggesting tumor suppressive activity of DLK1 both in vitro and in vivo." (PMID 26198328, 2015). "While studies on the Dlk1-Dio3 imprinting domain in hESCs have mainly focused on the field of tumor promotion, limited reports to date have validated the significance of this domain gene locus." (PMID 25879223, 2015). "In the present study, we also examined the methylation status of DMR and the expression of genes, snoRNAs and miRNAs in the Dlk1-Dio3 region of our HCC tumors compared with adjacent non-tumor tissues." (PMID 25217841, 2014). "CpG site cg17412258, 212 bp upstream of the DLK1 transcription start site, showed 4.32 fold higher methylation in the tumor samples relative to the adjacent normal tissue samples, with a 5% higher average methylation index for the other CpG sites." (PMID 23890537, 2013). "Epigenetic alteration at the imprinted domain, defined by DLK1 (AL132711) and GTL2 (AL117190) genes, has been reported in human neoplasia, causing alteration in the expression of GTL2, although loss of imprinting for DLK1, has not been found." (PMID 18478077, 2008). "The restricted expression of DLK1 in normal adult tissues, combined with its cell-surface localisation and functional relevance in tumour biology, makes it an attractive therapeutic target, particularly in endocrine malignancies where targetable options remain limited." (PMID 42023826, 2026). "Post‐operative blood samples showed a significant reduction in DLK1 levels after tumor resection." (PMID 40035383, 2025). "In all cases, there was a strong positive correlation between tumor size and serum DLK1 levels." (PMID 40035383, 2025). "Thus, the Dlk1+/Gpc3+/Afp+ progenitor-like cells potentially represent a tumour-initiating state for branch 1 tumours." (PMID 39112713, 2024). "Furthermore, our data demonstrate high expression of Notch ligands (DLL3, DLK1) in tumor cells, indicating a possible role for these ligands in the recruitment and regulation of TAN and TAM within the bone metastatic microenvironment." (PMID 38358826, 2024). "Studies have shown that both mouse and human PanIN and PDAC express DCLK1, and DLK1 may mark tumor-initiating cells in a variety of tumor types." (PMID 39839479, 2024). "The direct link we propose between DLK1, NOTCH1 signaling, and ABCB1 expression also suggest that ABCB1 inhibition could improve anti-tumor responses to DLK1-directed ADCs." (PMID 39416174, 2024). "Although a large proportion of tumour cells were found along this Dlk1/Gpc3/Afphi branch, there were a small but substantial number of tumour cells along Notch1/Tgfb1hi branch 2, which was characterized by another progenitor and stem marker: Nes (which encodes nestin)." (PMID 39112713, 2024). "Moreover, an increase in serum soluble DLK1 levels in HCC patients was found to correlate with tumor size." (PMID 39769389, 2024). "Indeed, DLK1 vaccination also promoted enhanced deposits of Type-1 skewed CD8+ T cells that likely contributed to durable anti-tumor responses through epitope spreading in a majority of mice." (PMID 37849752, 2023). "It is suggested that overexpression of Dlk1 enhances tumor cell stemness and invasiveness in-vitro." (PMID 35676718, 2022). "They suggested that the hypoxic microenvironment of the tumor could induce DLK1 expression, a positive regulator of Wnt signaling." (PMID 35805898, 2022).
tumor (continued). "Therefore, NOTCH1 activation levels, as negatively regulated by DLK1, appeared critical for the function of this receptor as an oncogenic or as a tumor suppressor protein in MDA-MB-231 cells." (PMID 35163478, 2022). "Interestingly, some studies also indicate that DLK1 participates in the tumor progression of neuroblastoma, ovarian high-grade serous carcinoma, and lung cancer mediated the activation of NOTCH1." (PMID 35456435, 2022). "Additionally, DLK1 has been shown to suppress PPARγ, a widely known tumor growth, invasion, and EMT inhibitor." (PMID 35805898, 2022). "Inhibition of DLK-1 (e.g. vaccination against DLK-1) led to tumor vascular normalization." (PMID 34957538, 2021). "Besides, the addition of miR-127 suppressed xenograft tumor growth via suppressing DLK1 protein level in nude mice." (PMID 32051829, 2020). "Co-staining against HIF-1α, a hypoxia marker, and CD44, a marker previously used to define perivascular and perinecrotic tumor areas, revealed that DLK1 localized prevalently in perivascular and hypoxic niches, with previously unreported nuclear localization specifically in these areas." (PMID 32205867, 2020). "Collectively, these data indicate that DLK1 is a potential prognostic factor for AML patient OS and the tumor-suppressing abilities of MEG3 may be overwhelmed by DLK1 expression and/or CpG site-specific signatures of its downstream miRNAs." (PMID 30876483, 2019). "Our comparison of the mRNA and miRNA expression profiles of mutated and wild‐type KMT2D suggested that two signaling pathways (FOX1–miR‐1224‐5p–DLK1 and HIF/GATA5–miR‐133a‐3p–DRD5) may mediate the tumor suppressive effect of the KMT2D mutation." (PMID 30984543, 2019). "In terms of tumor stage and size, DLK1 and NCOR1 showed a synergistic effect in nucleus." (PMID 31661545, 2019). "The Snail-mediated Dlk1-Dio3 locus repression in tumor-infiltrating immune cells might contribute to a disease-promoting, chronic inflammatory microenvironment." (PMID 30190790, 2018). "Increased DLK1 levels may become oncogenic in NSCLC by upregulating cell cycle machinery, which has been proposed to be highly associated with tumor invasion." (PMID 29435111, 2018). "A Snail-mediated repression of the Dlk1-Dio3 locus predominantly in tumor-infiltrating immune cells would hence affect only a minor proportion of the cells comprising the total tumor mass, although it would probably still be detectable by microarray analysis of whole tumor mRNA." (PMID 30190790, 2018). "HCC samples were considered positive for each HPC marker if more than 5% of tumour cells in a single section were stained; as a result, 18.3%, 7.1%, 14.3%, and 8.0% patients were found to have high levels of DLK1, NCAM, EpCAM, and CK19 in tumours, respectively." (PMID 29774107, 2018). "Therefore, in this study we assessed HCC heterogeneity according to the presence of HPC markers DLK1, NCAM, EpCAM, and CK19 in the tumour, and analysed their association with HCC prognosis." (PMID 29774107, 2018). "Reintroduction of DLK1 into DLK1-null RCC cell suppresses tumor growth in nude mice." (PMID 29069869, 2017). "The results showed that Dlk1 knockdown also could inhibit tumor progression in a diethylnitrosamine (DEN) induced mouse HCC model." (PMID 27683116, 2016). "To determine whether DLK1 knockdown can suppress tumor growth when tumors already exist, we inoculated nude mice with Huh-7 and Hep3B stable cells expressing inducible DLK1 shRNA." (PMID 27683116, 2016). "The Dlk1-Dio3 region appears critical for the pluripotency of iPSCs and tumor promotion." (PMID 25879223, 2015). "However, both the relationship between DLK1 and tumor metastasis and its mechanism are poorly characterized." (PMID 24621612, 2014). "The role of DLK1 in tumor progression requires investigating in further detail." (PMID 23946804, 2013).
tumor (continued). "Evidence also suggests that DLK1 may inhibit tumor cell differentiation and increase tumorigenic potential, although the underlying mechanisms causing these effects remain unclear." (PMID 23946804, 2013). "The elevated expression of DLK1 has been observed in several tumor types, including MDS and AML." (PMID 23946804, 2013). "In four of five tumours with hypermethylation of the GTL2 promoter DMR, heterozygosity at a DLK1 SNP (c.564T>C) (n=−2) or at closely linked microsatellite markers (D14S598, D14S1426, D14S749 and D14S1006) excluded 14q32 maternal allele loss as a cause of the GTL2 promoter DMR hypermethylation." (PMID 15798773, 2005). "They speculated that HB could develop from a bipotential precursor, characterized by the expression of DLK1, and that the degree of Wnt or Notch pathway activation could depend on the stage of developmental arrest and therefore, be useful for tumor subtypes classification." (PMID 35805898, 2022). "miR-129-5p has been found downregulated in NSCLC; however, its upregulation inhibits tumor growth and generates chemoresistance by downregulating DLK1 (delta-like non-canonical Notch ligand 1), which suggest that miR-129-5p and DLK1 may play a relevant role in NSCLC and its treatment." (PMID 35406675, 2022). "Besides, the expressions of miR-127 and DLK1 protein were measured in collected tumor tissues." (PMID 32051829, 2020). "Besides, the accumulation of miR-127 decreased tumor growth by suppressing DLK1 in vivo." (PMID 32051829, 2020). "As the Snail levels were modulated in the tumor epithelial cells and the Dlk1-Dio3 locus expression changes occurred in the tumor immune compartment, we aimed to understand how the Snail-mediated Dlk1-Dio3 locus repression in immune cells might be regulated in terms of cellular communication." (PMID 30190790, 2018). "In general, our results suggested that targeting DLK1 might inhibit the tumor growth via initiating cell differentiation of HCC CSCs, although molecular mechanisms by which DLK1 knockdown contributes differentiation therapy of HCC should be further investigated." (PMID 27683116, 2016). "Furthermore, in an orthotopic xenograft mouse model, adenovirus-mediated DLK1 knockdown could significantly reduce tumor size, as shown by in vivo imaging approach." (PMID 27683116, 2016). "Our previous work on metastasis-associated genes in human lung SCC suggested that DLK1 might function in tumor metastasis (data not shown)." (PMID 24621612, 2014). "If DLK1 maintains tumor cells in a stem cell-like state, the relatively long lifespan of stem cells will allow undifferentiated tumor cells to accumulate and the stable genetic and epigenetic changes that ultimately result in tumor malignancy to be perpetuated." (PMID 23946804, 2013). "However, the role of DLK1 and its mechanism in tumor growth remains to be fully elucidated." (PMID 23946804, 2013). "As for novel therapies, a α-polarized DC vaccine targeting PC antigen DLK1, protected mice from CRC progression by enhancing CD8+ T Cell mediated anti-tumor immunity." (PMID 40248695, 2025). "Genes with reported anti-tumor functions, including SCGB1D2 (Secretoglobin Family 1D Member 2, lipophilin B), FKBP5, CD52, DLK1, GALNT9, GNG2, GDNF, and TMEM35A, were significantly upregulated after CUDC-907 + MPA treatment and validated by RT-PCR." (PMID 41262902, 2025). "Among the top 100 deregulated genes, Wnt-associated genes such as LGR5, DKK1, and NKD1, as well as the HB-related genes DUSP9, DLK1, PEG3, PEG10, IGF2BP1, and IGF2BP2 were consistently upregulated in tumor samples." (PMID 40968384, 2025). "A correlation was observed between DLK1 CNA and pathological features indicative of more-aggressive disease and poorer outcomes (larger tumor size and advanced AJCC tumor stages)." (PMID 39595993, 2024).
tumor (continued). "When transplanted into mice, only mLPS1 gave rise to LPS; these cells highly expressed tumor stem cell markers (CD133) and mesenchymal stem cell markers (CD73, CD90, CD105, and Delta-like homolog 1 [DLK1])." (PMID 39723387, 2024). "Ligand-receptor analysis uncovered several significant interaction channels, including ligands that were distinctively upregulated in the tumor cells such as CD24, VEGFA, DLL3, and DLK1." (PMID 38358826, 2024). "HCC patients with higher levels of blood tumor markers (AFP, AFP-L3) have a higher expression of DLK1, along with simultaneous co-expression with other HPC markers." (PMID 39769389, 2024). "DLK1 knockdown in HCC cell lines was shown to suppress colony formation in vitro and tumor growth in vivo." (PMID 39769389, 2024). "MiR-484 constitutes a tumor-suppressor miRNA and plays a role in the epithelial-to-mesenchymal transition (EMT) by targeting the DLK1 gene." (PMID 37445798, 2023). "Tumor cells from patient #4001 were characterized by overexpression of AFP, GPC3, DUSP9, DLK1, GLUL, and AXIN2, a marker of Wnt/β-catenin pathway activation." (PMID 37932266, 2023). "The expression of DLK1 and PTTG1 transcripts correlates with several normal and tumor tissues, including normal pituitary tissue and samples of pituitary adenoma or fetal liver and HCC." (PMID 35805898, 2022). "Vaccines targeting both DLK1 and DLK2 show superior antitumor benefits by promoting CD8+ T cells infiltrations and tumor vascular normalization." (PMID 35456435, 2022). "This was further supported by Western blot analyses on infigratinib‐resistant tumours, where there was an increase in CSC markers such as SOX9, YAP1 and DLK1 particularly in the later stages of resistance." (PMID 33179425, 2021). "In cytokine and chemokine array analyses the overexpression of Lrp5 reduced the levels of several tumor-promoting factors in CM, including CXCL2, GM-CSF, IL6, LIF, DLK1 and MRP with an increase in IL27, a tumor-suppressing cytokine." (PMID 33859739, 2021). "DLK1/MEG3 locus promoted somatotroph differentiation and inhibited tumor proliferation in PIT1(+) patients, furthermore, the level of DLK1 played a critical role in the trend of somatotroph or lactotroph differentiation." (PMID 33472171, 2020). "With the appearance of DLK1 and NCOR1 in the nucleus, the proportion of early tumor stage increased, and the proportion of large tumor size decreased." (PMID 31661545, 2019). "From DN negative samples to DN positive samples, with the emergence of DLK1 and NCOR1 in the nucleus, the proportion of early tumor samples (stage I) significantly increased (P=0.013)." (PMID 31661545, 2019). "In contrast, the combination of ΔNβ-catenin, YAPS127A, and c-Met (BYM model) induced larger and multiple liver nodules throughout the liver surface and the tumor nodules highly expressed both GREB1 and DLK1." (PMID 31462641, 2019). "Since we performed the IHC of NCOR1 and DLK1 on the same batch of samples, we investigated the co-location of DLK1 and NCOR1 in tumor cells." (PMID 31661545, 2019). "We examined several miRNAs from the Dlk1-Dio3 region using a microarray-based expression analysis of 17 CRC tissues and matched non-tumor adjacent tissues." (PMID 29304823, 2018). "In this study, we analysed the association between clinicopathological characteristics of HCC patients and tumour expression of four HPC markers, EpCAM, NCAM, CK19, and DLK1." (PMID 29774107, 2018). "In this study, we employed human HCC xenograft tumor models and the DEN-induced mouse HCC model to address the therapeutic efficacy of targeting endogenous human or mouse DLK1 in HCC cells." (PMID 27683116, 2016). "Given their known functions and the findings in other cancers, DLK1 and MEG3 are good tumor-suppressor candidates." (PMID 25741387, 2014).
tumor (continued). "All five of the identified genes (DLK1, PLAGL1, SLC22A18, TP73, and WT1) have presumed tumor suppressing functions and taken together demonstrate a strong tendency towards higher methylation at the CpG sites assessed." (PMID 23890537, 2013). "Sequence analysis using genomic DNA from 40 primary HCC tumours revealed 16 specimens informative for MEG3 and 24 specimens informative for DLK1 (in total 31 informative cases)." (PMID 23145177, 2012). "The direct link we propose between DLK1, NOTCH1 signaling, and ABCB1 expression also suggests that ABCB1 inhibition could improve anti-tumor responses to DLK1-directed ADCs." (PMID 40595495, 2025). "Notably, whereas cells in the Notch1 TIC/tumor branch express ectopic NRAS at a level comparable with the OIS cluster, the Dlk1-type TIC/tumor branch shows a much lower NRAS expression." (PMID 40324881, 2025). "Our data suggest that DLK1 maintains adrenal steroidogenic cell differentiation, which is concordant with recent data from a spatial transcriptomic analysis of DLK1+ and DLK1− ACC tumor regions." (PMID 39416174, 2024). "Moreover, while we focused on the role of DLK1 in mediating ADC resistance in our functional studies, DLK1 is known to regulate cancer stemness and tumor progression." (PMID 39416174, 2024). "Interestingly, tumor growth inhibition and increased rates of CD8 cytotoxic tumor infiltrating lymphocyte (TIL) and vascular normalization have been achieved after therapeutic vaccination against DLK1 in RENCA-bearing mice." (PMID 39086395, 2024). "By contrast, Dlk1+ cells were detected in all tumours irrespective of time of onset (n = 15) but retained their hepatocytic morphology and were spatially distinct from NOTCH1/nestin+ regions, where Dlk1+ cells tended to exhibit lower NRAS expression." (PMID 39112713, 2024). "The protumour genes DLK1 and RCN1 were highly expressed in the CNVhigh area, which might be related to tumour progression and could be targeted for precision therapy." (PMID 39548559, 2024). "To help ensure specific targeting of tumor-derived blood vessels, we confirmed by PCR that the MC38 tumor cell line does not detectably express DLK1 but is present in MC38 in vivo tumors." (PMID 37849752, 2023). "We found that Epcam, Gpc3 and Dlk1 were highly expressed in a small percentage of cells ( < 25%) in tumor samples compared to normal control livers although not as remarkably as the erythroid genes (Gata1, Alas2, Rhd, Hba-a1)." (PMID 37414763, 2023). "As the DMR region of DLK1 is tissue-specific—showing different DMR-methylation profiles in placenta, liver, and tumor tissues —it may be also regulated differentially in the two sexes." (PMID 35063005, 2022). "In the current review we focus on the pituitary tumor transforming gene (PTTG1)/delta like non-canonical notch ligand 1 (DLK1) axis as a potential therapeutic target to attenuate the progression of these pathological conditions." (PMID 35805898, 2022). "Evaluation of raw gene transcripts per million for key upregulated genes with strong upregulation in tumor and PDX, and prior reported involvement in HB, including GPC3, DLK1, and IGF2, showed robust increase in HB tumor gene expression with further elevated expression in PDX tumors." (PMID 34497364, 2021). "We speculated that the DLK1/MEG3 locus promoted somatotroph differentiation and inhibited tumor proliferation of PitNETs." (PMID 33472171, 2020). "Data presented here do not link signaling from the soluble DLK1 to that of the intracellular fragment, however, both appear to be regulated by the hypoxic tumor microenvironment." (PMID 33142235, 2020). "Expression of GREB1 and DLK1 in the tumor lesions was higher than the nontumor regions, and their staining levels were correlated with the degree of differentiation." (PMID 31462641, 2019). "Our results suggest that the downregulation of the Dlk1-Dio3 locus genes occurs in the tumor-infiltrating immune cells rather than in the carcinoma cells expressing Snail." (PMID 30190790, 2018).